CCL2 (C-C motif chemokine ligand 2)
Diseases named in the same sentence as CCL2 in open-access papers (continued):
Sharing a sentence is not in itself a finding about the gene and the disease.
Sepsis (continued). "The data from the present study are distinct from a recent study we conducted in canine sepsis; however, where the concentration of CCL2 was highly discriminant for non-survival." (PMID 30105229, 2018). "Indeed, in mouse serum, mouse CCR2 protein (the receptor for CCL2) is necessary for expression of mouse IL6 protein that is increased by experimentally induced sepsis in mouse, and IL1 protein increases expression of CCL2 protein." (PMID 21906276, 2011). "This suggests that KC-like may not be a general biomarker for sepsis in all types of canine bacterial infections, and CCL2 or other blood biomarkers may also have a role in discriminating septic from nonseptic cases in pyometra." (PMID 39272157, 2024). "In canine studies modeling sepsis through injection of lipopolysaccharide (LPS), treated dogs had greater blood IL-6, IL-10, TNF-α, and KC-like concentrations up to 4-h post-injection and greater CCL2 up to 24-h post-injection, when compared to placebo-treated dogs." (PMID 31316998, 2019). "The in vitro neutralization of CCL2, CCL3 and CCL5 by mAbs inhibited γδ T lymphocyte chemotaxis towards the respective chemokines and lung homogenates obtained from CLP mice, suggesting that these chemokines coordinate γδ T cell in vivo migration into the lungs during severe sepsis." (PMID 26037291, 2015). "Although IGFBP6-mediated regulation of CCL2 is independent of IGF2, the potential involvement of IGF2-dependent pathways in IGFBP6’s modulation of sepsis progression remains an open question requiring systematic investigation." (PMID 40892465, 2025). "Expression levels of Selp, Ccl2 and Il1r1 were robustly increased by CLP sepsis irrespective of genotype, suggesting that endothelial MyD88 is not required for transcriptional responses to CLP in hippocampal vasculature, microglia and neurons." (PMID 26790027, 2016). "Also, the chemokines, CCL-2, CXCL-2, and cytokines, IL-1β and IL-6, were not affected by NK-2R blocking in sepsis." (PMID 21188216, 2010).
glioma (264 papers, 2008 to 2025). A benign or malignant brain and spinal cord tumor that arises from glial cells (astrocytes, oligodendrocytes, ependymal cells). "Glioma cells secrete IL-8 and CCL2 and induce glioma-associated macrophages (GAMs) to secrete TNF-α, which induces endothelial cell activation to promote tumor survival." (PMID 42135822, 2025). "CCL2 is found to be expressed in glioma, which causes nearby microglia to produce IL-6, resulting in a more infiltrative tumor." (PMID 41157253, 2025). "COX-2 and PGE2 are produced by microglia and macrophages, and PGE2 in the TME is linked to an increased expression of glioma-derived monocyte chemoattractant CCL2/MCP-1, leading to the active recruitment of TAMs." (PMID 38334650, 2024). "The level of CCL2 expression is linked to glioma aggressiveness in a CCL2-expressing CNS-1 glioma animal model." (PMID 36403059, 2022). "PGE2 in the TME is linked to increased expression of glioma-derived monocyte chemoattractant CCL2/MCP-1, leading to active recruitment of GAMs." (PMID 36776369, 2022). "Along with glioma cells, immune cells such as glioma-associated microglia and macrophages (GAMs) secrete CCL2 to recruit regulatory T-cells (Tregs) and MDSCs." (PMID 33919732, 2021). "Glioma cells secret CCL-2 to promote the activity of tumor-associated macrophages which suppressed the activities of cytotoxic T cells." (PMID 33959130, 2021). "These glioma-associated microglia and MΦ (GAM) are recruited by glioma cells, secreting several chemoattractants such as CCL2, Cx3CL1, SDF-1, and CSF-1, among others." (PMID 34445160, 2021). "In humans and in animal glioma models, increased CCL2 expression has been associated with high number of GAMs infiltrating tumor tissues, increased angiogenesis and tumor invasion, and poor clinical prognosis." (PMID 34504786, 2021). "Some investigators reported that CCL2 has been primarily recognized in gliomas among the chemokine pathways involved in tumor associated macrophage (TAM) chemoattraction." (PMID 34830041, 2021). "A study reports that low-grade glioma stem-like cells (GSCs) harboring BRAF kinase gene mutations (KIAA1549:BRAF fusion) express Ccl2 for circulating monocytes recruitment." (PMID 34671362, 2021). "Studies have further demonstrated that higher levels of MCP-1/CCL-2 are secreted GBMs as well as other glioma variants." (PMID 33204365, 2020). "It was the first TAM chemo-attractant identified in GBM; the level of CCL2 expression is associated with glioma grade." (PMID 32765498, 2020). "CCL2 participates in the transport of tumor-associated macrophages (TAM) in gliomas, which affects angiogenesis, invasion, local tumor recurrence and immunosuppression." (PMID 33014836, 2020). "In comparison, by using the model applied here, only cells of the tumor microenvironment (e.g., myeloid cells, endothelial cells) possess Ccr2-deficiency, while glioma cells still express Ccr2, hence retaining functionality towards CCL2 and other signals." (PMID 32668709, 2020). "Collectively, this study proved the critical role of CCR2 in migration to glioma with a result that gliomas in CCL2-deficient mice displayed reduction of both Treg and monocytic MDSCs infiltration." (PMID 31225500, 2019). "PGE2 production was associated with increased CCL2, which can attract suppressive myeloid cells to the glioma site." (PMID 24202450, 2013). "Additionally, in the glioma microenvironment, upregulation of CCL2 promotes the infiltration of tumor-associated macrophages, which, in turn, promotes the proliferation and survival of glioblastoma cells by transferring LDHA-containing extracellular vesicles." (PMID 39660865, 2025). "Notably, in the rat glioma model, a substantial association was found between invading microglial cells and elevated production of either MCP-1 or CCL2." (PMID 40727443, 2025). "Thus, highly expressed CCL2 was confirmed, and it was identified as a significant risk factor for OS rate in patients with gliomas." (PMID 39030882, 2024).
glioma (continued). "Therefore, a variety of cancers, e.g., glioma, breast tumors, or prostate cancer are associated with increased serum concentrations of CCL2." (PMID 33540898, 2021). "In addition, a senescence-associated gene signature including CCL2 was associated with a poor prognosis in human gliomas." (PMID 32346064, 2020). "Notably, approximately 70% of TAMs infiltrated glioma tissues independently of the CCR2/CCL2 signal which underlines the role of other important recruitment factors." (PMID 32668709, 2020). "In addition, the risk score was also positively associated with the expression of INF-γ, IL-6, CCL2 and HLA-A, suggesting that macrophages and T cell mediated immune response were involved in high-risk group of glioma patients." (PMID 30407923, 2018). "Glioma cells make matters worse by releasing factors like CSF-1, CCL2, and osteopontin, which further drive these macrophages into their tumor-supportive M2 state." (PMID 41583467, 2025). "Together, these data suggested that Fn promoted glioma growth by increasing the levels of N-acetylneuraminic acid and the expression of CCL2, CXCL1, and CXCL2." (PMID 39660865, 2025). "Astrocyte-derived CCL2 can bind CCR2 on glioma cells to maintain stemness characteristics by activating JAK2/STAT3-Notch signaling pathway." (PMID 40243478, 2025). "S100B can also maintain immunosuppressive microenvironmental characteristics of gliomas by chemotaxis of TAMs through the upregulation of CCL2." (PMID 40243478, 2025). "Circulating monocytes are recruited in gliomas via several growth factors and chemokines (like CSF-1, CCL2, CCL7, CCL20)." (PMID 41157253, 2025). "We also investigated the effects of naringenin on modulating the inflammatory molecules IL-6, CCL2, and TNF-α associated with immunosuppression in glioma cells." (PMID 40149846, 2025). "In parallel, chemokine gradients (e.g., CCL22, CCL2) actively recruit regulatory T cells (Tregs) to the glioma TME, where they increase further under the effect of immunoregulatory enzymes such as indoleamine 2,3-dioxygenase (IDO)." (PMID 41583467, 2025). "Both in vivo and in vitro experiments demonstrated that Fn, as a key bacterium enriched in glioma tissue, promotes glioma proliferation and increases the expression of CCL2, CXCL1, and CXCL2." (PMID 39660865, 2025). "The radiomics quantitatively analyzes images to assess tumors noninvasively, and it can be well‐suited to predict the CCL2 expression level in glioma patients." (PMID 39030882, 2024). "Human glioma cells induce microglia to secrete and release IL-6 through CCL2/CCR2 axis, thus promoting glioma invasion." (PMID 38229178, 2024). "Our group has previously identified C-C motif chemokine 2 (CCL2) as a glioma-derived T-reg chemoattractant acting on chemokine receptor 4 (CCR4) in a murine orthotopic glioma model." (PMID 39046599, 2024). "An increased CCL2 expression has been correlated with reduced overall survival in human glioma patients." (PMID 39046599, 2024). "To determine if canine Tregs can stimulate CCL2 expression in canine glioma cells, we performed co-culture experiments." (PMID 39046599, 2024). "Our group and others have previously shown that glioma-derived CCL2 is a crucial chemoattractant responsible for Treg recruitment into the glioma microenvironment in murine models and human tissues." (PMID 39046599, 2024). "We and others have previously shown that glioma-derived C-C Motif Chemokine Ligand 2 and 22 (CCL2 and CCL22) is a critical chemoattractant responsible for Treg recruitment into the GBM microenvironment." (PMID 39046599, 2024). "Recently, we demonstrated a robust increase of CCL2 in the brain tissue of canine patients bearing high-grade glioma." (PMID 39046599, 2024). "Compared with control-derived macrophages, glioma-derived TAMs produced higher levels of IL-6, IL-8, CCL2, and CCL8." (PMID 38370418, 2024). "CCL2 mRNA was expressed in all glioma cell lines, and expression increased when exposed to Tregs but not CD4 + helper T-cells." (PMID 39046599, 2024).
glioma (continued). "Glioma cells increase the secretion of CCL2 to recruit immune-regulatory cells in human glioma models." (PMID 39046599, 2024). "The data indicated that CDYL depletion decreased glioma development and promoted immune pathways and expression of chemokine ligands (e.g., chemokine [C-C motif] ligand 2 [CCL2])." (PMID 39519018, 2024). "Using murine models, we determined that CCL2 induces Treg recruitment into the glioma microenvironment through the CC chemokine receptor type 4 (CCR4) expressed on Tregs." (PMID 39046599, 2024). "Tumor-infiltrating lymphocytes (TILs): In GBM, TILs often exhibit dysfunction and exhaustion caused by factors released by glioma and microenvironmental cells, including TGF-β, IL-10, and CCL2, which recruit Tregs, MDSCs, and TAMs to the tumor site." (PMID 38610954, 2024). "The chemokine (C‐C motif) ligand 2 (CCL2) is a promising predictor for glioma malignancy and progression." (PMID 39030882, 2024). "Tumor-associated myeloid cells: Tumor-associated microglia and macrophages (TAMs) are the main infiltrating population in GBM, attracted towards the tumors in response to high concentrations of various chemoattractants secreted by glioma cells, including CCL2." (PMID 38610954, 2024). "Canine Tregs increased migration toward human recombinant CCL2 and glioma cell line-derived supernatant." (PMID 39046599, 2024). "A comparative study of murine glioma synthesized CCL2 was reported to facilitate the recruitment of CCR2+ Ly6C+ monocytic MDSCs (M-MDSCs) to the tumor site, while CCL2-deficient tumor site witnessed a significant reduction in MDSCs infiltration." (PMID 38360737, 2024). "Among the cytokines regulated by ZBTB18, CCL2 is known to be released by the glioma cells and to recruit myeloid-derived suppressor cells." (PMID 39516530, 2024). "Another feedforward mechanism involves glioma-derived MCP-1/CCL2, which triggers the release of IL-6 from microglia, a ligand for signal and activator of transcription 3 (STAT3) pathway in gliomas." (PMID 38254796, 2024). "Our group has previously identified C-C motif chemokine 2 (CCL2) as a glioma-derived T-reg chemoattractant acting on chemokine receptor 4 (CCR4) in a murine orthotopic model of glioma." (PMID 38947002, 2024). "SYK affects the expression of CCL2, IL1RA, and IL8 and participates in the formation of the glioma immune microenvironment, which is considered to be an independent risk factor for glioma patients." (PMID 38594692, 2024). "Targeting the CCL2/CCR2 axis has been shown to reduce tumor infiltrating macrophages in pre-clinical glioma studies." (PMID 38515213, 2024). "In gliomas, CCL2's production is vital for recruiting immunosuppressive CCR4+ Tregs and CCR2+ Ly‐6C+ monocytic myeloid‐derived suppressor cells." (PMID 39706820, 2024). "In this regard, CCL2 inhibitors or CCR2 antagonists have shown promising results in preclinical models of gliomas, while other subtypes of CC chemokines are still under investigation." (PMID 36980182, 2023). "Glioma progression is also supported by astrocytic release of CC chemokine ligand 2 (CCL2) and colony-stimulating factor 1 (CSF1), leading to recruitment of tumor-associated macrophages with a pro-tumor phenotype." (PMID 38275375, 2023). "The infiltration of peripheral monocytes/brain-intrinsic microglia to the glioma sites is mediated by the interaction between C-C chemokine receptor type 2 (CCR2) expressed on monocytes and C-C motif chemokine ligand 2 (CCL2/MCP-1) expressed by glioma cells." (PMID 37111742, 2023). "Then, we performed IHC staining analysis for CD68 and CCL2 in an in-house cohort, and the results showed that high BCL2A1 expression was significantly associated with CD68 and CCL2 expression in gliomas." (PMID 37889551, 2023). "Glioma cells constitutively secrete C–C motif chemokine ligand 2 (CCL2), which converts Th2 lymphocytes into immunosuppressive T regulatory (Treg) cells and macrophages into the pro-neoplastic M2 phenotype." (PMID 37686020, 2023).
glioma (continued). "Preclinical data show that a CCL2-neutralizing antibody prolongs the survival in mouse and human glioma xenograft models by inhibiting TAM infiltration." (PMID 37705736, 2023). "A number of molecules also influence macrophage infiltration of the central nervous system via interactions with CCL2 and thereby affect glioma pathogenesis." (PMID 37153567, 2023). "In the tumor microenvironment of human gliomas, CCL2 has been shown to recruit both CCR4+ Treg and CCR2+ Ly6C+ monocytic myeloid-derived suppressive cells." (PMID 38213329, 2023). "A different study of the U251 glioma cell line, however, suggested differently: after CCL2 knockdown, glioma cells exhibited significantly decreased proliferation and migration, and significantly increased apoptotic activity, as compared to control cells." (PMID 37153567, 2023). "In glioma U251 cells transfected with CCL2 siRNA, there was decreased cell proliferation, cell cycle arrest, and a significant increase in apoptosis-associated proteins such as Caspase-3 and Caspase-7." (PMID 36980182, 2023). "(1c), the first term represents glioma recruitment of MDSCs to the microenvironment by secreting the chemokines CCL2 and CCL7, which are ligands for the CCR2 receptor expressed by MDSCs." (PMID 38099947, 2023). "In human GBM, microglia and macrophages are recruited to the tumor by glioma-derived chemoattractants (e.g., chemokine ligand-2 (CCL2))." (PMID 37368789, 2023). "Among the 12 significant genes involved in the immunosuppression of GBM, CCL2 recruits Tregs and myeloid-derived suppressor cells, which play a critical role in the immunosuppressive glioma microenvironment." (PMID 38019838, 2023). "CCL2 expression is dramatically elevated in glioma U87 cells grown with microglia, which enhances glioma cell invasion." (PMID 36146527, 2022). "Low-grade gliomas highly express CCL2-4, high-grade gliomas express CCL5, while diffuse midline gliomas have basal expression of all chemokines." (PMID 35464481, 2022). "Recombinant and glioma-derived CCL2 and CCL7 induce the migration of CCR2+/CX3CR1+ MDSCs with similar efficacy." (PMID 36685592, 2022). "KR158B, KR158B CCL2 KD or KR158B CCL7 KD glioma cell lines were implanted in Ccr2+/RFP/Cx3cr1+/GFP mice, and flow cytometry analysis of tumors and bone marrow was conducted 4.5 weeks post-implantation." (PMID 36685592, 2022). "In the other chemokine genes, CCL2 secreted by glioma cells promotes tumor growth and migration, its expression is correlated with GAMs accumulation in GBM." (PMID 35985661, 2022). "A previous study suggested that CCL2/CCR2 plays an important role in the proliferation of glioma cells." (PMID 36058942, 2022). "Anti-CCL-2 antibodies were reported to drastically reduce the infiltration of microglia in mice with glioma." (PMID 36146527, 2022). "CCL2 was significantly down-regulated after SU4312 treatment, and the number of M2 macrophages was subsequently decreased, indicating that the effect of SU4312 on the glioma-immune microenvironment is mediated by the down-regulation of CCL2." (PMID 36013004, 2022). "On the other hand, glioma-cells release chemoattractant molecules that recruit TAMs and promote tumor growth: CCL2, CCL7 (or MCP-3), IL-33, GDNF (Glial cell line-derived neurotrophic factor), MCP-1 (CCL2), SDF-1 (CXCL12), CSF-1 (M-CSF), GM-CSF, and EGF." (PMID 35269652, 2022). "CCR2+/CX3CR1+ cells are also reduced within KR158B gliomas upon combination targeting of CCL2 and CCL7." (PMID 36685592, 2022). "ELISA analysis of the conditioned media of KR158B cells determined that after 24 hours, glioma cells plated at 500 cells/uL had produced 11.1ng/mL of CCL2 and 1.9ng/mL of CCL7." (PMID 36685592, 2022). "A study revealed that the significance of IL-1β lies in the IL-1β/CCL2/IL-6 interaction between microglia as well as glioma cells." (PMID 35419058, 2022).